TUBB7P (tubulin beta 7 pseudogene)
Synonyms: TUBB4Q
Gene: Unprocessed pseudogene on chromosome 4 (189,982,523 to 189,984,871, reverse strand). Ensembl gene ENSG00000251297.
Diseases named in the same sentence as TUBB7P in open-access papers:
TUBB7P is named in the same sentence as 1 disease in open-access papers, as found by Europe PMC text mining. Sharing a sentence is not in itself a finding about the gene and the disease. The quoted sentences say what the papers report.
tumor (1 paper, 2018). "We found that tumor tissues express significantly higher levels of TUBB and TUBB3 and significantly lower levels of TUBB2B, TUBB6, and TUBB7P pseudogene." (PMID 30126203, 2018). "Analyzing expression profile of BC tumors and tumor-adjacent normal breast tissues showed upregulation of TUBA1A, TUBA1C, TUBB and TUBB3 and downregulation of TUBB2A, TUBB2B, TUBB6, TUBB7P pseudogene, and TUBGCP2 in the tumor tissues compared to the normal breast tissues." (PMID 30126203, 2018).